PARP3 (poly(ADP-ribose) polymerase family member 3)
Description:
Mono-ADP-ribosyltransferase that mediates mono-ADP-ribosylation of target proteins and plays a key role in the response to DNA damage. Mediates mono-ADP-ribosylation of glutamate, aspartate or lysine residues on target proteins. In contrast to PARP1 and PARP2, it is not able to mediate poly-ADP-ribosylation. Involved in DNA repair by mediating mono-ADP-ribosylation of a limited number of acceptor proteins involved in chromatin architecture and in DNA metabolism, such as histone H2B, XRCC5 and XRCC6. ADP-ribosylation follows DNA damage and appears as an obligatory step in a detection/signaling pathway leading to the reparation of DNA strand breaks. Involved in single-strand break repair by catalyzing mono-ADP-ribosylation of histone H2B on 'Glu-2' (H2BE2ADPr) of nucleosomes containing nicked DNA. Cooperates with the XRCC5-XRCC6 (Ku80-Ku70) heterodimer to limit end-resection thereby promoting accurate NHEJ. Suppresses G-quadruplex (G4) structures in response to DNA damage. Associates with a number of DNA repair factors and is involved in the response to exogenous and endogenous DNA strand breaks. Together with APLF, promotes the retention of the LIG4-XRCC4 complex on chromatin and accelerate DNA ligation during non-homologous end-joining (NHEJ). May link the DNA damage surveillance network to the mitotic fidelity checkpoint. Acts as a negative regulator of immunoglobulin class switch recombination, probably by controlling the level of AICDA /AID on the chromatin (By similarity). In addition to proteins, also able to ADP-ribosylate DNA: mediates DNA mono-ADP-ribosylation of DNA strand break termini via covalent addition of a single ADP-ribose moiety to a 5'- or 3'-terminal phosphate residues in DNA containing multiple strand breaks.
Synonyms: ARTD3; hPARP-3; pADPRT-3; ADPRT3; ADPRTL3; IRT1; ADPRTL2
Tractability: Small molecule: an approved drug acts on it; a structure with a bound ligand is known; a high-quality ligand is known; it belongs to a druggable protein family. PROTAC: it is named in the literature on targeted protein degradation; ubiquitination databases record sites on it; a small molecule that binds it is known.
Target class: Enzyme; Transferase
Gene: Protein-coding gene on chromosome 3 (51,942,252 to 51,948,871, forward strand). Ensembl gene ENSG00000041880.
Subcellular location: Nucleus; Chromosome; Cytoplasm, cytoskeleton, microtubule organizing center, centrosome; Cytoplasm, cytoskeleton, microtubule organizing center, centrosome, centriole
Subcellular location (Human Protein Atlas): Nuclear bodies; Nucleoplasm
Gene Ontology:
Molecular function: NAD DNA ADP-ribosyltransferase activity; NAD+ poly-ADP-ribosyltransferase activity; NAD+-protein mono-ADP-ribosyltransferase activity; NAD+-protein-aspartate ADP-ribosyltransferase activity; NAD+-protein-glutamate ADP-ribosyltransferase activity; NAD+-protein-lysine ADP-ribosyltransferase activity; protein binding; catalytic activity
Biological process: DNA ADP-ribosylation; double-strand break repair; double-strand break repair via nonhomologous end joining; positive regulation of double-strand break repair via nonhomologous end joining; protein auto-ADP-ribosylation; protein localization to site of double-strand break; protein poly-ADP-ribosylation; regulation of mitotic spindle organization; telomere maintenance; negative regulation of isotype switching; negative regulation of telomere maintenance via telomerase; negative regulation of DNA metabolic process
Cellular component: chromosome; nuclear body; nucleoplasm; nucleus; site of double-strand break; nucleolus; centriole; centrosome
Genetic constraint (gnomAD): Loss-of-function variants: 46 observed, 58.77 expected, observed/expected ratio (o/e) 0.78, 90% interval 0.62 to 1. The upper end of that interval is the gene's LOEUF score, 1, which puts it in group 4 of 6, group 1 being the genes least tolerant of losing a copy. Missense variants: 663 observed, 706.79 expected, observed/expected ratio (o/e) 0.94, 90% interval 0.88 to 1. Synonymous variants: 252 observed, 277.75 expected, observed/expected ratio (o/e) 0.91, 90% interval 0.82 to 1.01.
Homologues: Orthologues: chimpanzee PARP3 (98% identical), macaque PARP3 (92% identical), pig PARP3 (83% identical), dog PARP3 (82% identical), mouse Parp3 (80% identical), rat Parp3 (78% identical), guinea pig PARP3 (76% identical), rabbit PARP3 (75% identical), tropical clawed frog parp3 (59% identical), zebrafish parp3 (55% identical), Caenorhabditis elegans tank-1 (22% identical). Paralogues in human: PARP2 (35% identical), PARP1 (34% identical).
Diseases named in the same sentence as PARP3 in open-access papers:
PARP3 is named in the same sentence as 34 diseases in open-access papers, as found by Europe PMC text mining. Sharing a sentence is not in itself a finding about the gene and the disease. The quoted sentences say what the papers report.
breast cancer (18 papers, 2016 to 2025). A primary or metastatic malignant neoplasm involving the breast. "Moreover, PARP3 has been associated with promoting chromosomal rearrangements and enhancing breast cancer aggressiveness." (PMID 40595727, 2025). "PARP3 was reported to be associated with the progression of gliomas and breast cancer." (PMID 37350936, 2023). "PARP3 overexpression is associated with a poor prognosis in patients with breast cancer following chemotherapy and thus, PARP3 inhibitors may be a potential therapeutic strategy for the treatment of breast cancer." (PMID 31500199, 2019). "PARP3 regulates TGFβ-induced cytoskeletal rearrangement, leading to formation of lamellipodia, the numbers of which are elevated in BRCA1-deficient breast cancer cells." (PMID 40741921, 2025). "Some studies have indicated that PARP3 is overexpressed in aggressive breast cancer and primary glioblastoma." (PMID 41008918, 2025). "The protein levels of MDC1, PSMB1, PSMB9, PSMD2, PSMD7, and PSMD14 were increased, while that of PARP3 was decreased in breast cancer tissues compared with normal tissues." (PMID 37350936, 2023). "In our study, the PARP3, POLR2K, PSMB1, and PSMD2 genes were significantly associated with the overall survival of patients with breast cancer, and the high expression levels of POLR2K, PSMB1, and PSMD2 were related to low survival rates." (PMID 37350936, 2023). "In contrast, the expression of PARP3 were significant declined in breast cancer patients (P < 0.05)." (PMID 37350936, 2023). "Herein, we discovered that PARP3 expression plays a protective role in the development of breast cancer (HR < 1)." (PMID 36713553, 2022). "Then, we further investigated the prognosis effect of PARP3 in patients with breast cancer with both proteomic and genomic data, and the results were consistent, which mean that PARP3 is still a protection factor to patients in proteomic level (p = 0.047)." (PMID 35479398, 2022). "Researches reported that PARP3 is a driver gene to TGFβ-induced epithelial-to-mesenchymal transition and its inhibitors sensitize breast cancer cells to vinorelbine which was used in the treatment of metastatic breast cancer." (PMID 35479398, 2022). "In breast cancer, Poly(ADP-ribose) polymerase 3 (PARP3) has been identified as a key driver of tumor aggressiveness exemplifying its selective inhibition as a promising surrogate for clinical activity onto difficult-to-treat cancers." (PMID 36109561, 2022). "PARP-3 expression is higher in breast cancer cells with a mesenchymal phenotype and correlates with the expression of vimentin, a mesenchymal marker." (PMID 33923319, 2021). "Gene copy number variation (CNV) analysis of SETD2, BAP1, PARP-3 and PBRM1 within a panel of nine breast cancer cell lines demonstrated single copy number loss of all candidate genes within five (56%) cell lines (including 21NT cells)." (PMID 28977912, 2017). "Collectively, these data revealed that PARP3 endows human mammary epithelial cells and breast cancer cells with stem cell properties." (PMID 27579892, 2016). "In this study, we examined the transcriptional and protein expression level of PARP3 in human breast cancer cell lines of distinct subtypes expressing various levels of EMT traits." (PMID 27579892, 2016). "PARP3 expression is higher in breast cancer cells of the mesenchymal phenotype and correlates with the expression of the mesenchymal marker Vimentin while being in inverse correlation with the epithelial marker E-cadherin." (PMID 27579892, 2016). "An impaired upregulation of Snail and Vimentin and an inefficient downregulation of E-cadherin was also observed in the breast cancer MCF7 cells upon PARP3 silencing." (PMID 27579892, 2016). "Based on our initial observation that PARP3 levels are generally higher in the mesenchymal-like basal B breast cancer cell lines that display EMT properties and correlate with the EMT score, we aimed to decipher the contribution of PARP3 in this process." (PMID 27579892, 2016).
breast cancer (continued). "In breast cancer cell lines, PARP3 expression correlates with mesenchymal cell phenotype." (PMID 40741921, 2025). "Moreover, later studies have shown that PARP3 expression is positively correlated with the invasive basal-like and mesenchymal subtypes of breast cancer, where is is significantly increased." (PMID 41008918, 2025). "suggest that the production of ROS, triggered by TGF‐β, activates PARP3 in breast cancer cells." (PMID 38613355, 2024). "Here, we investigate the prognosis effect of PARP3 in patients with breast cancer." (PMID 35479398, 2022). "In addition, PARP3 has also been shown to control the TGFβ- and ROS-driven epithelial-to-mesenchymal transition and stemness in human breast cancer cell lines." (PMID 31500199, 2019). "Due to the high frequency of gene copy number loss within breast cancer cells, our results provide additional evidence that SETD2, BAP1, PBRM1 and PARP-3 may function as tumour suppressors in breast cancer cells." (PMID 28977912, 2017). "In order to investigate the functional role of SETD2, BAP1, PBRM1 and PARP-3 in regulating hTERT transcription, we examined the effect of forced, stable overexpression of candidate genes on pre-spliced hTERT expression within 21NT breast cancer cells." (PMID 28977912, 2017). "Collectively, these data suggested that PARP3 is upregulated in breast cancer cell lines displaying a mesenchymal-like gene expression profile and raised the question of whether PARP3 might regulate the switch between the epithelial and mesenchymal phenotype." (PMID 27579892, 2016). "Thus arguing that PARP3 is involved in primary spheroid bodies formation of mammary epithelial and breast cancer cells." (PMID 27579892, 2016). "In the course of our studies aimed to decipher the biological properties of PARP3, we compared the expression of PARP3 in a series of human breast cancer cell lines of distinct subgroups with predominantly luminal (luminal), mixed luminal/basal (basal A) and basal (basal B) features." (PMID 27579892, 2016). "Therefore, the biofunction of PARP3 in the progression of breast cancer deserves further research." (PMID 36713553, 2022). "In conclusion, the results from the present study provide evidence to suggest that BAP1 and possibly PARP-3 repress hTERT transcription within breast cancer cells, which supports the hypothesis that multiple sequences on human chromosome 3p may be responsible for regulating hTERT transcription." (PMID 28977912, 2017). "In contrast, the expression levels of PARP3 and PSMB9 were lower in breast cancer cells than in normal cells." (PMID 37350936, 2023). "Subsequently, we explored the protein levels of MDC1, PARP3, PSMB1, PSMB9, PSMD2, PSMD7, and PSMD14 in normal breast tissues and breast cancer tissues." (PMID 37350936, 2023). "In breast cancer cells, poly ADP-ribose polymerase 3 (PARP3) plays an important role in inducing EMT and CSC phenotypes by regulating the TG2-snail-E-cadherin axis in response to ROS." (PMID 37033606, 2023). "Our results suggest that focusing on PARP3, PSMB1, PSMD7, and PSMD14 and their roles in immunotherapy is a reasonable strategy for breast cancer treatment." (PMID 37350936, 2023). "We analyzed a prognostic model based on seven DDR genes, PSMD2, PSMD7, PSMD14, PARP3, MDC1, PSMB1, and PSMB9, reflecting an enhanced level of predicting the survival and prognosis of patients with breast cancer." (PMID 37350936, 2023). "The hazard ratio of five genes (RBBP8,PARP3, ENDOV, UBE2V2, and DDB2) was <1, which plays a protective role in developing breast cancer." (PMID 36713553, 2022). "The complex interactions between PARPs and EMT-regulating pathways are exemplified by the role of PARP-3 in TGF-β and ROS-dependent EMT, as well as the stem-like feature expression in human mammary epithelial and breast cancer cells." (PMID 33923319, 2021).
breast cancer (continued). "We next performed real-time qPCR on the breast cancer cell lines and normal breast tissues using primer sequences specific to the candidate genes SETD2, BAP1 PBRM1 and PARP-3 (Figure 2Ci-2Civ)." (PMID 28977912, 2017). "In conclusion, our data provide evidence that PARP3 drives TGFβ-mediated EMT and stem cell development in normal mammary and breast cancer cells and that these activities involve a PARP3 response to the generation of ROS." (PMID 27579892, 2016). "Next, we analyzed PARP3-overexpressing MCF10A cells for the presence of tumor initiating CD44high/CD24low population characteristic for the mammary and breast cancer stem cells." (PMID 27579892, 2016). "Similar to PARP2, not much is known about the potential role of PARP3 in cancer cell death resistance apart from a study that reported poor prognosis of patients with PARP3 overexpressing breast cancers who received chemotherapy." (PMID 33922595, 2021). "Since olaparib, a potent PARP-1, PARP-2 and PARP-3 inhibitor, has shown remarkable efficacy in BRCA mutated breast cancer 65, 66, a phase I/II trial tested the combination of 300 mg of olaparib twice daily and eribulin (at standard dose and schedule) in TN advanced BC patients." (PMID 31762800, 2019). "In the present study, overexpression of BAP1, but not PARP3, PBRM1 or SETD2, was associated with significant (but not complete) repression of hTERT transcription within 21NT breast cancer cells." (PMID 28977912, 2017). "Here we report that PARP3 also plays an integral role in TGFβ and reactive oxygen species (ROS) dependent epithelial-to-mesenchymal transition (EMT) and stem-like cell properties in human mammary epithelial and breast cancer cells." (PMID 27579892, 2016). "We established a seven-gene prognostic model comprising MDC1, PARP3, PSMB1, PSMB9, PSMD2, PSMD7, and PSMD14 genes, which provides a basis for further exploration of a population-based prediction of prognosis and immunotherapy response in patients with breast cancer." (PMID 37350936, 2023). "In addition, we have demonstrated that SETD2, BAP1, PBRM1 and PARP-3 are all down-regulated in the breast cancer cell line 21NT when compared to normal cells (HMEC), making them prime targets for tumour suppression / telomerase repression in breast cancer." (PMID 28977912, 2017).
glioblastoma (7 papers, 2012 to 2025). The most malignant astrocytic tumor (WHO grade IV). "Collectively, these data suggest that PARP3 is required to regulate the stability of cytoskeletal microtubules under hypoxia and its absence increases the susceptibility of glioblastoma cells to microtubule destabilizing agents." (PMID 36109561, 2022). "In agreement with this latter result, we show here that PARP3 is implicated in the regulation of hypoxia signaling pathways in glioblastoma cells." (PMID 36109561, 2022). "Since PARP3 and G9a control the expression of common hypoxia-associated genes, we speculated on a possible functional cooperation between both enzymes in cell response to hypoxia, a hallmark of glioblastoma invasion." (PMID 36109561, 2022). "In glioblastoma cells, PARP3 has been identified as a novel interactor and regulator of the histone methyltransferase G9a (also known as EHMT2)." (PMID 40741921, 2025). "Here we explored the role of PARP3 in the oncogenicity of glioblastoma, the most aggressive type of brain cancer." (PMID 36109561, 2022). "Here we aimed to decipher the functional role of PARP3 in the oncogenicity of glioblastoma, the most aggressive primary brain cancer." (PMID 36109561, 2022). "In glioblastoma cells, PARP3 was proposed to enhance the transcriptional activity of FOXM1 to confer glioblastoma cell radioresistance." (PMID 36109561, 2022). "To further decrypt the functions of PARP3 in glioblastoma and identify gene regulatory pathways controlled by PARP3, we performed a comparative RNAseq of the WT-LN229 and PARP3−/− LN229 cells." (PMID 36109561, 2022). "In the future, these findings will inspire novel therapeutics strategies for the use of PARP3-specific inhibitors combined with microtubules targeting agents to overcome tumor hypoxia as a barrier to effective cancer treatment in glioblastoma." (PMID 36109561, 2022). "Our data reveal an accelerated hypoxic stress-induced decrease in α-tubulin acetylation and detyrosination in the PARP3 knockout glioblastoma cells and upon PARP3 inhibition, indicating weakened cytoskeleton microtubules." (PMID 36109561, 2022). "Silencing PARP3 expression improves the therapeutic efficacy of radiotherapy in glioblastoma." (PMID 41008918, 2025). "For example, elevated PARP3 levels have been observed in primary glioblastoma biopsies." (PMID 41008918, 2025). "This suggests that PARP3-specific inhibitors in combination with microtubule-targeting agents could represent a potential therapeutic approach for glioblastoma treatment." (PMID 40741921, 2025). "Given the increasing appreciation for the role of PARP3 in tumor aggressiveness, we aimed to investigate whether PARP3 might be involved in the pathogenesis of glioblastoma, one of the most malignant and aggressive brain cancer in adults." (PMID 36109561, 2022). "In consequence, the absence of PARP3 sensitizes glioblastoma cells to microtubule destabilizing anti-cancer agents." (PMID 36109561, 2022). "The absence of PARP3 did not alter cell proliferation nor the in vivo tumorigenic potential of glioblastoma cells." (PMID 36109561, 2022). "As a result, the absence of PARP3 markedly increases the sensitivity of glioblastoma cells to microtubule-destabilizing agents providing a new therapeutic avenue for PARP3 inhibition in brain cancer therapy." (PMID 36109561, 2022). "Following this result, we hypothesized that the absence of PARP3 may affect the sensitivity of glioblastoma cells to microtubule-destabilizing agents." (PMID 36109561, 2022). "We found that PARP3 expression is predominant in all but not in two (U87MG, SF767) glioblastoma cell lines and poorly detectable in the astrocytoma cell line LNZ308." (PMID 36109561, 2022).
triple-negative breast carcinoma (5 papers, 2021 to 2025). An invasive breast carcinoma which is negative for expression of estrogen receptor (ER), progesterone receptor (PR), and human epidermal growth factor receptor 2 (HER2). "In BRCA1-deficient triple-negative breast cancer cell lines, the enzymatic activity of PARP3 (ARTD3) was involved in promoting cell survival and proliferation and correlated with increased AKT phosphorylation." (PMID 34725336, 2021). "Along a similar line of evidence, the mono-ADP-ribosyltransferase PARP3 has been reported to positively regulate the Rictor/mTORC2 signalling in models of triple negative breast cancer." (PMID 39847113, 2025). "In BRCA1-deficient triple-negative breast cancer (TNBC) cells, PARP3 inhibition exacerbates centrosome amplification and genome instability via limitation of Rictor protein level by ubiquitination, thus efficiently represses oncogenic Rictor/mTORC2 signaling." (PMID 35982899, 2022).